AR (androgen receptor)
Diseases named in the same sentence as AR in open-access papers (continued):
Sharing a sentence is not in itself a finding about the gene and the disease.
cancer (continued). "This review summarizes and discusses the available data indicating the involvement of androgens as well as androgen receptor and related signals in ovarian carcinogenesis and cancer growth." (PMID 30791431, 2019). "The contrasting processes of cell differentiation and proliferation are both driven by androgens in the prostate, but in a context‐dependent way that seems reprogrammed during cancer progression by coactivators and corepressors modulating the AR cistrome." (PMID 31162796, 2019). "In summary, AR pathway activity was increased in cancer-adjacent, hyperplasia and PCa tissue and was nearly always associated with PI3K pathway activity in hyperplasia and variably in primary PCa." (PMID 30733525, 2019). "That study indicated that the androgen receptor binds to the F7 promoter near the ATG translation start codon, which suggests that the androgen receptor directly activates F7 gene expression in cancer cells." (PMID 30797223, 2019). "A consequent problem of using these potent anti-AR drugs is that they impose a strong selective pressure that pushes cancers to find alternative mechanisms distinct from those regulated by AR, or that substitute for vital AR functions." (PMID 31142021, 2019). "In three cases, the positive staining for AR was detected in ACC cancer cells, indicative of AR ectopic expression in the ACC." (PMID 30382367, 2019). "Collectively, our findings underscore a novel role of CD44 signaling in the maintenance of stemness and progression of cancer through SOX2 in AR‐independent PC3 cells." (PMID 30206982, 2019). "For cell lines, androgens are critical for the development and maintenance of normal and cancer tissue, and the androgen receptor (AR) is the main therapeutic target for PCa13." (PMID 30828436, 2019). "Strong ROCK1 staining was found in 3% of AR-negative, but in 27% of strongly AR positive cancers, in 13% of ERG-negative but in 25% of ERG positive cancers, and in 12% of PTEN normal but in 26% of PTEN deleted cancers." (PMID 31557128, 2019). "All prostate cells, both normal glandular epithelium and cancer cells, are strictly dependent on androgens, as they express the human androgen receptor (AR)." (PMID 30642011, 2019). "A more accurate model of clinical cancer requires, at the very least, an androgen-insensitive, AR-positive cancer cell line." (PMID 30621175, 2019). "Only 2% of AR-negative, but 33% of strongly AR expressing cancers had strong BAP1 expression (p<0.0001)." (PMID 31903168, 2019). "In ER positive breast cancers, androgen receptor (AR) and androgenic enzymes are known to antagonize ERα, suppressing carcinoma progression." (PMID 31847455, 2019). "Most of the carcinomas (174/180, 97%) contained at least one AR-positive neoplastic cell, whereas only few FMCs (6/180, 3%) were completely devoid of AR expression." (PMID 31888566, 2019). "Briefly, ATAD2 is a nuclear coactivator of ER and AR crucial for assembly of chromatin-modifying complexes and proliferation of hormone-responsive cancer cells." (PMID 29301281, 2018). "Similar to other cancers, PCa cells need iron for their survival, including the use of iron for the activity of enzymes that control androgen receptor (AR) transcriptional activity, which is a known promoter of PCa." (PMID 30538952, 2018). "Docetaxel resistance can develop through numerous mechanisms, including androgen receptor (AR) signaling, activation of prosurvival pathways and the acquisition of a cancer stem cell morphology." (PMID 29662635, 2018). "Many transcriptional factors, such as Myc, ERα, and AR, exert oncogenic functions to drive cancer cell proliferation." (PMID 29342868, 2018).
cancer (continued). "In a recent study, Cochrane and colleagues concluded that an AR/ER ratio ≥2 was an independent predictor of disease-free and cancer-specific survival." (PMID 29651273, 2018). "We thank Dr. Jianhui Wu (Mcgill University) and Dr. Hiroyuki Seimilya (Cancer Chemotherapy Center, Japan) for kindly providing AR expressing plasmids." (PMID 30555332, 2018). "Mechanistic investigation has found out that hypoxia-induced PHF8 can serve as an essential histone demethylase activity-dependent AR coactivator, promoting AR signaling pathway and cancer progression." (PMID 29699590, 2018). "These AR-independent pathways can promote cancer cell survival and growth and appear to be a major androgen-independent driver of AR-regulated gene expression in castration-resistant prostate cancer." (PMID 29731997, 2018). "SEMA3C expression levels increase in castration‐resistant prostate cancer (CRPC), where it functions to promote cancer cell growth and resistance to androgen receptor pathway inhibition." (PMID 29348142, 2018). "Since we observed the inhibitory effect of SINE on AR/ARv signaling, we tested the anti-cancer activity of SINE." (PMID 30450161, 2018). "In this review we have presented and discussed many findings showing that ligand activation of AR inhibits the cellular proliferation in most of ER-positive BC and induce the cancer growth in most of ER-negative BC." (PMID 30210453, 2018). "For example, RNF6 mediates the polyubiquitination of androgen receptor and estrogen receptor thus increasing their activity and promotes cancer cell proliferation." (PMID 29997504, 2018). "AR is normally present also in normal tissue, and its presence is normally higher in well-differentiated cancers than undifferentiated tumors." (PMID 29651273, 2018). "A more precise model of clinical cancer requires, at the very least, an androgen-insensitive AR-positive cancer cell line." (PMID 29614830, 2018). "In PA a focal immunohistochemical expression of AR was described, while its expression was detected in 90% of Ca ex PA, suggesting an AR role in malignant tumor evolution." (PMID 29385707, 2018). "MMP-9 is one of the key factors, which promote cancer metastasis and it is also a transcriptional target of AR, commonly present in metastatic PCa." (PMID 30134822, 2018). "Characterization of multiple proteins involved in AR signaling, cancer stem cells (CSC), and castration resistance in 1° CRPC reveal changes unique to each model." (PMID 30190514, 2018). "Our data suggest a new therapeutic potential to block cancer metastasis by targeting AR, EGFR and MMP-9 pathways in subsets of PCa patients." (PMID 30134822, 2018). "Studies have detected high androgen receptor (AR) expression levels in 60%~70% ER-negative BC cases, thus highlighting the importance of AR in the biology of this cancer subtype." (PMID 30217192, 2018). "In this review, aberrant splicing events in cancer-associated genes, namely BCL2L1, FAS, HRAS, CD44, Cyclin D1, CASP2, TMPRSS2-ERG, FGFR2, VEGF, AR and KLF6, will be discussed." (PMID 30463359, 2018). "Thus, promoter hypermethylation does not seem to be a prevalent mechanism underlying microRNA downregulation in this cancer model, and other causes, whether genetic, epigenetic or microenvironment-related (e.g., abnormal AR signaling), are likely to be more frequent." (PMID 29599847, 2018).
cancer (continued). "Prx II regulates stemness-associated characteristics of cancers via several pathways, mainly including VEGF/VEGFR/STAT3, Ras/FoxM1, JNK, Wnt/β-Catenin, Hedgehog and androgen (AR)/androgen receptor signaling." (PMID 30177619, 2018). "Androgen receptor (AR) is located on the X chromosome and is expressed in a diverse range of normal and cancer tissues." (PMID 29716628, 2018). "Because AR maintains the proliferation of ER-negative BC cells, the use of AR antagonists seems to be a logical choice for treating this cancer subtype." (PMID 30217192, 2018). "Whilst this indicates that AR expression in the prostate stroma is an important prognostic biomarker, how AR influences cancer progression is unclear." (PMID 29721186, 2018). "Either, the cancer cells produce intracellular androgen for their survival or they utilize a ligand independent activation of the androgen receptor, which leads to activation of downstream survival mechanisms." (PMID 29370088, 2018). "In analysis of AR expression, there were 86 cancer recurrences, 78 deaths from EAC and 83 deaths from any cause identified during follow-up." (PMID 30450159, 2018). "In the future, we hope to identify new anti-androgen approaches to eliminate OCSCs or to inhibit cancer cell growth in patients with high AR expression." (PMID 29716628, 2018). "This again emphasizes the importance of first recognizing the morphological features of the dimorphic cell before interpreting either AR or GCDFP-15 positivity as indicative of apocrine metaplasia or carcinoma." (PMID 28965222, 2018). "17β-HSD2 immunoreactivity was detected in the cytoplasm of carcinoma cells, while AR immunoreactivity was detected in the nuclei of carcinoma cells." (PMID 29642629, 2018). "ARHGAP15 immunoreactivity was frequently detected in the cytoplasm of carcinoma cells, and was positively correlated with that of Rac1 and androgen receptor labeling index." (PMID 29534468, 2018). "SM22 can act as a cancer repressor by modulating the secretion of matrix metalloproteinase 9 (MMP9) or the AR signaling pathway." (PMID 29029391, 2017). "This is an example of ligand-independent activation via phosphorylation of AR, which is thought to be one of the main mechanisms of AR activation in cancer." (PMID 28415597, 2017). "In summary, we have demonstrated that miR-34b expression is lower in African-American compared to Caucasian tissue samples and is inversely correlated with high AR level leading to cell proliferation and cancer progression." (PMID 28039468, 2017). "It is important, however, to distinguish this from the potential role of decreased stromal AR in cancer progression and metastasis (see Section 2)." (PMID 28117763, 2017). "Rather, it is involved in several mechanisms, including regulation of cancer genes and AR cofactors as well as partial modulation of EMT." (PMID 28241429, 2017). "EGCG can restrict cancer cell growth, suppress androgen receptor functions and regulate cancer cell survival, angiogenesis and movement." (PMID 28225779, 2017). "It has been suggested that ARVs must work in concert with AR-FL to regulate expression of AR target genes and stimulate growth of castration-resistant cancers." (PMID 29181019, 2017). "This transcriptional activation function of AR is important in the normal sexual development of the male gender as well as the progression of cancer." (PMID 28475115, 2017). "This is followed by the determination of the role of upstream pathways (i.e. Cdk1 and ERK1/2 pathways) on AR activation and their effects on cancer specific survival (CSS)." (PMID 28415597, 2017). "Enrichment analysis revealed that the most significant molecular networks were the TGF beta signalling pathway, Androgen receptor signalling pathway, Transcriptional misregulation in cancer, etc.." (PMID 29208006, 2017).
cancer (continued). "AR signaling remains active in castration-resistant disease, and a recent study used chromatin immunoprecipitation (ChIP) coupled to sequencing (seq), to identify a gene signature of putative AR-target genes in this lethal form of cancer." (PMID 28415728, 2017). "In that respect, it is similar to more familiar cancer targets such as oestrogen receptor, androgen receptor and progesterone receptor." (PMID 28481952, 2017). "When these networks were merged, AR appears to be the key node for those two cancer-related networks." (PMID 28487351, 2017). "In the context of PCA, GAS5 promotes cancer cell death and prevents binding of the androgen/AR-complex to target DNA by sequestering the complex." (PMID 28241429, 2017). "The goal of these therapies is to diminish the availability of DHT activated androgen receptor (AR) to promote cancer cell proliferation and growth through AR specific gene activation." (PMID 28673330, 2017). "AR is expressed in many cell types and the androgen/AR signaling has been found to promote tumorigenesis and metastasis in several types of cancers including prostate, bladder, kidney, lung, breast, liver and ovary." (PMID 27741511, 2017). "Transcriptional control of key players of cancer and AR signaling by KDM3A such as KLK3, NKX3-1, MYC were validated by chromatin immunoprecipitation coupled with quantitative real time polymerase chain reaction (ChIP-qRT-PCR)." (PMID 28416760, 2017). "Nitric oxide is a product of certain events within cancer cells, inhibits AR expression and activity, and plays a role in cancer progression and metastasis." (PMID 28117763, 2017). "AR signaling is involved in a number of normal physiologic processes, and there is varying levels of evidence for its role in promoting cancer growth and progression across an array of malignancies." (PMID 28085048, 2017). "For example, AR (androgen receptor), a target gene of hsa-miR-3148, was enriched in pathways in cancer." (PMID 28904974, 2017). "A major downstream effector of TNK2 in hormonally regulated cancers has been AR, which also points to the potential of ER as another TNK2-interacting entity." (PMID 27902967, 2017). "One of these signaling modules, HGF-c-MET, is frequently overexpressed in AVPCa and AR inhibitor treated cancers." (PMID 28103576, 2017). "Previous evidence suggested the potential anti-cancer activity of luteolin and apigenin by downregulating the AR and AKT signaling in PCa cells." (PMID 29066975, 2017). "Aberrant AR function and cross-talk with factors that activate the AR pathway are assumed to be involved in this cancer evolution." (PMID 28264478, 2017). "Due to its role in cancer progression, several drugs have been proposed to target AR as an alternative treatment." (PMID 28903437, 2017). "Reciprocal activation has been observed between the IGF-1R and the AR signaling pathways, supporting the rationale of simultaneous inhibition in cancer treatment." (PMID 28447314, 2017). "Abiraterone acetate and enzalutamide strongly target the AR pathway and improve cancer specific survival in the case with CRPC." (PMID 28264478, 2017). "This comparison confirmed significant positive enrichment in cancer for all but 2 AR target gene sets (SMARCA4- and NCOA2-dependent)." (PMID 28826481, 2017). "Most CRPC patients still relapse after a year of such treatment, and AR activity appears to be restored again in at least a subset of the cancers." (PMID 28036278, 2017). "GR can bind to and drive the expression of a subset of AR target genes, thus allowing the cancer to progress despite ongoing AR blockade." (PMID 28891793, 2017). "KLK4 expression in cancer cell lines, has been shown to be regulated by activation of both androgen receptor (AR) and progesterone receptor (PR)." (PMID 29249975, 2017). "The mechanisms that drive this progression are not fully understood, but AR activity, at least in a subset of cancers, appears to be restored again." (PMID 28036278, 2017).
cancer (continued). "Oxadiazole derivatives examined in the current study disrupted AR N-C and AR-cofactor interactions and suppressed AR transcriptional activity as well as AR-mediated cancer cell growth, both in vitro and in vivo." (PMID 29050220, 2017). "This alteration reflects the transition of androgen-dependent PCa to CRPC and enhancement of cancer survival during ADT by upregulating the AR and HER3 signaling pathways." (PMID 29066975, 2017). "This compensatory response allows cancer cells to survive in a low testosterone environment and the reactivated AR signaling axis continues to play a role after neoplastic transformation." (PMID 28361666, 2017). "Meanwhile, preclinical evidence has strongly suggested the involvement of androgen receptor (AR) signaling in bladder tumorigenesis and cancer progression." (PMID 28241422, 2017). "After adjustment for other prognostic factors, multivariate analyses confirmed high AR expression as a favorable biomarker for cancer-specific survival." (PMID 29108248, 2017). "Our results also raise the possibility that other semaphorins or their receptors fall under AR, GATA2, or FOXA1 regulation, especially given that many semaphorin family members are implicated in cancer." (PMID 28038451, 2017). "AR-FL continues to be expressed in the cancer cells that arise from prostatic epithelium as well as some cancer associated stromal cells." (PMID 29181019, 2017). "Docetaxel resistance can develop through numerous mechanisms, including androgen receptor (AR) signalling, activation of prosurvival pathways and the acquisition of a cancer stem cell (CSC) morphology." (PMID 28133913, 2017). "Having shown the distinct roles of AR in different epithelial cell types in prostate homeostasis, we then explored its cell-type-specific function during cancer initiation." (PMID 28112153, 2017). "In a study evaluating AR transcript levels using real-time PCR, it was found that AR mRNA expression levels correlated with pathologic T stage and cancer specific survival." (PMID 28085048, 2017). "This recalls the emerging role for STAT3 and AR in cancer stemness and the overlap in NANOG binding sites with a subset of ARBSs." (PMID 28826481, 2017). "For instance, AR-positive tumors constitute only 33% of high-grade carcinomas compared to 61% of low-grade carcinomas." (PMID 29108248, 2017). "Since the early studies with tritiated DHT exchange assays carried out by the McGuire's laboratory in the seventies, the presence of AR protein in cancer specimens has been detected." (PMID 26556855, 2016). "Along the same line, the development of selective estrogen receptor modulators and selective androgen receptor modulators has yielded compounds with improved anti-cancer action and reduced side effects." (PMID 27713909, 2016). "Most of these cancers co-express different degrees of the Progesterone Receptor (PR) and the Androgen Receptor (AR)." (PMID 26797644, 2016). "Polycomb-independent regulatory functions of EZH2 have been also recognized in other cancer models, where the protein cooperates with other transcription factors (such as the androgen receptor or NF-κB) to exert oncogenic properties." (PMID 27563817, 2016). "AR is expressed in a sub-set of ER-negative breast cancers but also in an even more significant proportion of ER-positive cancers." (PMID 26797644, 2016). "Of the 190 TNBCs for which both AR and PD-L1 staining results were available, 15 (7.9%) expressed both AR and PD-L1 in cancer cells by IHC." (PMID 28721372, 2016). "KEGG analysis of the microarray data revealed that the levels of cancer-related pathways increased in an AR expression–dependent manner." (PMID 27340775, 2016). "It has been recently emerged that BM-MSCs recruited to tumors secrete the chemokine CCL5 (also called RANTES), which acts in a paracrine fashion to suppress AR signaling in neighbouring cancer cells." (PMID 26880966, 2016).